DICER1 (dicer 1, ribonuclease III)
Diseases named in the same sentence as DICER1 in open-access papers (continued):
Sharing a sentence is not in itself a finding about the gene and the disease.
Anxiety (4 papers, 2014 to 2025). Intense feelings of nervousness, tension, or panic often arise in response to interpersonal stresses. "Deletion of Dicer1 in the adult brain reduced the abundance of mature miRNAs, but did not cause neuronal death or abnormalities in motor function, anxiety, or circadian rhythm, for up to 14 weeks after induction of the Dicer1 mutation." (PMID 24894914, 2014). "Deletion of Dicer1 in the gut ameliorates Aβ pathology but may also inhibit mitochondrial respiration in the brain of AD mice, and even induce anxiety of mice." (PMID 40926280, 2025). "Notably for our study, DICER1 has been shown to mediate stress-induced anxiety through its regulation of microRNA-34 in the amygdala." (PMID 24586686, 2014). "However, intestinal Dicer1 deletion, which may have reduced total secreted miRNA in the gut, has the potential to inhibit mitochondrial energy production in the brain and increase anxiety of App-knock-in mice." (PMID 40926280, 2025). "In behavior tests, deletion of intestinal Dicer1 induced anxiety symptoms without improving cognitive function in AD mice." (PMID 40926280, 2025).
heart failure (4 papers, 2019 to 2023). Inability of the heart to pump blood at an adequate rate to meet tissue metabolic requirements. "Interestingly, DICER1 knockdown, which was previously associated with the development of heart failure, is critical for canonical microRNA biogenesis." (PMID 37507877, 2023). "Both molecules involved in cytoplasmic pre-microRNA processing, DICER1 (FC = −1.32, p ˂ 0.01) and TARBP2 (a gene that encodes TRBP; FC = 1.54, p ˂ 0.05), were found to be deregulated in ischemic origin heart failure observed in the patients." (PMID 37507877, 2023).
Hodgkins lymphoma (4 papers, 2016 to 2025). A heterogeneous group of malignant lymphoid neoplasms of B-cell origin characterized histologically by the presence of Hodgkin and Reed-Sternberg (HRS) cells in the vast majority of cases. "We have also successfully combined our pipeline with literature review and functional studies to identify DICER1 as a candidate predisposing gene in one Hodgkin lymphoma family." (PMID 32211398, 2020). "We have already successfully implemented this pipeline to identify DICER1 as a candidate predisposing gene in familial Hodgkin lymphoma and are confident that our pipeline can be applied to the NMTC families in a similar manner." (PMID 31614935, 2019). "Our study further expands this understanding by showing that dysregulation of DICER1 and DROSHA is a common feature in hematologic malignancies, not only in myeloid neoplasms but also in lymphoid disorders such as Hodgkin lymphoma." (PMID 41463093, 2025).
larynx cancer (4 papers, 2015 to 2019). A primary or metastatic malignant neoplasm involving the larynx. "The rs3742330 AG and rs13078 TT genotypes of DICER1 are correlated with increased risk of larynx cancer." (PMID 26688807, 2015). "Additionally, rs13078 genetic variants in DICER1 have been reported to be related to other diseases, such as gestational hypertension and larynx cancer." (PMID 31354628, 2019). "This is the first report considering the association of the risk of larynx cancer and SNPs of the following polymorphisms: DROSHA (rs6877842), DGCR8 (rs3757, rs417309, and rs1640299), RAN (rs14035), XPO5 (rs11077), DICER1 (rs13078 and rs3742330), and TARBP2 (rs784567)." (PMID 26688807, 2015).
leukemia (4 papers, 2013 to 2025). A malignant (clonal) hematologic disorder, involving hematopoietic stem cells and characterized by the presence of primitive or atypical myeloid or lymphoid cells in the bone marrow and the blood. "In this leukemia, the rs13078 DICER1 variant (a single nucleotide polymorphism located in the 3′‐UTR of the DICER1 gene) was extensively examined." (PMID 40127989, 2025). "Leukemia arose in hematopoietic cells that expressed Dicer1 but had acquired other genetic abnormalities." (PMID 26543325, 2015). "Dicer1-deletion in immature osteoprogenitors also down-regulated Sbds, the gene responsible for Schwachman-Diamond syndrome (SDS), a human disease characterized by bone marrow failure and predisposition to leukemia." (PMID 35885544, 2022). "The induction of MDS and leukemia by Dicer1 selective deletion is not proving that MDS is caused by deranged MSCs but is rather suggestive that bone marrow MSC deregulations are sufficient to induce MDS." (PMID 24386000, 2013). "Several reports have shown the elevated levels of DICER1 expression in samples from the bone marrow of AML patients and leukemia cell lines, confirmed on both mRNA and protein levels." (PMID 40127989, 2025). "Interestingly, deleting Dicer1 in mature osteoblasts did not induce either MDS or leukemia, demonstrating that very specific alterations in the bone marrow are required for niche-induced oncogenesis." (PMID 26543325, 2015).
Obesity (4 papers, 2015 to 2024). Accumulation of substantial excess body fat. "Our previous work demonstrated that CamKCreERT2-dependent inactivation of the Dicer1 gene causes hyperphagic obesity both in male and female DicerCKO mice, with identical onset time and dynamics, but a slightly stronger extent of weight gain in females." (PMID 35873003, 2022). "Previously, we showed that Dicer1 deletion-associated hyperphagic obesity is strongly dependent on over-activation of the PI3K-Akt-mTOR pathway." (PMID 35490865, 2022). "Since obesity in DicerCKO mice is associated with the loss of the Dicer1 gene both in AgRP and POMC neurons, while miR-15-5p is highly expressed in POMCCre-GFP neurons, we sought to genetically inactivate this microRNA in POMCCre-Cas9-GFP cells during adulthood." (PMID 35873003, 2022). "In our previous studies, we showed that the mixture of ten microRNAs comprising mmu-miR-15a/b-5p, mmu-mir-26a/b-5p, mmu-mir-27b-3p, mmu-miR-29a-3p, mmu-miR-93-5p, mmu-miR-103/107-3p, mmu-miR-206-3p and mmu-miR-320-3p can counteract Dicer1 deletion-mediated hyperphagic obesity." (PMID 35873003, 2022). "Furthermore, we identified a group of candidate microRNAs including miR-103–3p preventing PI3K-Akt-mTOR pathway over-activation and thus protecting against hyperphagic obesity induced by Dicer1 deletion in the mouse hypothalamus." (PMID 35490865, 2022).
osteosarcoma (4 papers, 2017 to 2025). A usually aggressive malignant bone-forming mesenchymal neoplasm, predominantly affecting adolescents and young adults. "Notably, our case excluded DICER1 mutations (associated with pediatric central nervous system tumors), EWSR1 rearrangements (a hallmark of Ewing sarcoma), and MDM2 amplification (common in liposarcoma and osteosarcoma), highlighting the molecular distinctiveness of HGMS." (PMID 40242239, 2025). "We also found that the shRNA-mediated depletion of Aha1 led to decreased levels of Dicer1 protein in GM00637 human skin fibroblast and U2OS human osteosarcoma cells." (PMID 35736213, 2022).
post-traumatic stress disorder (4 papers, 2015 to 2022). An anxiety disorder precipitated by an experience of intense fear or horror while exposed to a traumatic (especially life-threatening) event. "Here the authors show significantly reduced levels of DICER1 in individuals having post-traumatic stress disorder and comorbid depression suggestive of a role in the molecular mechanism of the condition." (PMID 26632874, 2015). "A study conducted on peripheral blood mononuclear cells from post-traumatic stress disorder patients concluded that the chronic inflammation observed in these individuals could be triggered by downregulation of Ago2 and Dicer1, which impairs the generation of mature miRNA." (PMID 34991639, 2022). "Here, through genome-wide differential gene expression survey of post-traumatic stress disorder (PTSD) with comorbid depression (PTSD&Dep), we find that blood DICER1 expression is significantly reduced in cases versus controls, and replicate this in two independent cohorts." (PMID 26632874, 2015).
prostate adenocarcinoma (4 papers, 2008 to 2021). "Our results were consistent with the results reported for prostate adenocarcinoma, which suggested that Dicer1 expression was upregulated and affected tumor invasion characteristics." (PMID 33763118, 2021). "In contrast, a higher level of DICER1 in prostate adenocarcinoma accounted for up regulation of 39 of 45 differentially expressed miRNAs." (PMID 20459673, 2010).
renal cell carcinoma (4 papers, 2013 to 2021). "The miR-SNP rs3742330 in DICER1 contributes to T-cell lymphoma, renal cell carcinoma, oral premalignant lesions, and CRC19,63–65." (PMID 30833603, 2019). "The miRNA-SNP of rs3742330 of DICER1 has been identified for its association with the cancer outcome of CRC, T-cell lymphoma, oral premalignant lesions and renal cell carcinoma.The AA allele of rs3742330 located in the DICER1 gene exhibited a significantly increased risk of CRC." (PMID 26147304, 2015).
uterine cancer (4 papers, 2013 to 2023). Primary or metastatic malignant neoplasm involving the uterine corpus and/or the cervix. "The similar enrichments from independent largescale cancer cohorts strongly imply preferred impacts of DICER1 hotspot alleles in the uterine cancer setting." (PMID 31417090, 2019). "For example, a number of recent reports have found that DICER1 expression is lost in subsets of epithelial ovarian and uterine cancers and that reduced levels of DICER1 play a key role in determining clinical outcomes." (PMID 23641362, 2013).
angiosarcoma (3 papers, 2021 to 2024). A malignant tumor arising from the endothelial cells of the blood vessels. "Angiosarcoma is frequently associated with mutations in Dicer1, a ribonuclease enzyme essential for processing precursor miRNAs (pre-miRNAs) into mature functional miRNAs, and also has been implicated in angiosarcoma pathogenesis." (PMID 38826780, 2024). "Studies in mice have demonstrated that biallelic loss of Dicer1 predisposes endothelial cells to angiosarcoma formation, highlighting the critical role of DICER1 in maintaining proper miRNA biogenesis." (PMID 38826780, 2024). "Furthermore, biallelic deletion of Dicer1, a crucial enzyme for miRNA biogenesis, has been associated with the development of highly aggressive angiosarcomas." (PMID 38826780, 2024). "Compound mutant mice using aP2-Cre to drive recombination resulting in biallelic Dicer1 deletion or the combination of oncogenic KrasG12D activation and Cdkn2a deletion result in angiosarcoma from the transformation of endothelial cells." (PMID 34535684, 2021). "Studies demonstrated that biallelic Dicer1 deletion can lead to aggressive and metastatic angiosarcoma, even in the absence of additional oncogenic mutations." (PMID 38826780, 2024).
Arthritis (3 papers, 2018 to 2021). Inflammation of a joint. "Very recently, the downregulation of DICER1 gene and several RA-related mature miRNA expressions was reported in synovial fibroblasts from RA patients, while DICER1-deficient mice with K/BxN serum-transfer arthritis also displayed an unbalanced miRNA profiles and an enhanced inflammatory response." (PMID 31275058, 2019). "In RA, the decrease of DICER1 expression aggravates the symptoms in the mouse model of joint inflammation, and the lack of DICER1 causes the decrease of RA-related miRNA expression." (PMID 33841401, 2021). "Gain or loss of function from individual arthritis-related miRNAs such as miR-155 could also lead to similar expression regulation of proinflammatory proteins including MMP3 and MMP13, which suggested that partial function of DICER1 could be achieved through its downstream miRNAs." (PMID 31275058, 2019).
carcinosarcoma (3 papers, 2020 to 2021). A malignant tumor composed of a mixture of carcinomatous and sarcomatous elements. "IHC staining of 6 EC cases (5 endometrioid carcinoma and 1 carcinosarcoma) with DICER1 hotspot mutations only identified ARID1A loss in one endometrioid carcinoma case, but neither SMARCA4 nor ARID1B was lost in any of the 6 cases." (PMID 33052929, 2020). "In the uterus, DICER1 alterations are not limited to ERMS but have also been identified in a significant number of uterine adenosarcomas and few cases of carcinosarcoma." (PMID 33846547, 2021).
Carney complex (3 papers, 2019 to 2023). Carney complex (CNC) is characterized by spotty skin pigmentation, endocrine overactivity and myxomas. "Other syndromes with less frequency, including Attenuated familial adenomatous polyposis (AFAP), DICER1, and the Carney complex (CNC), predispose to thyroid tumors." (PMID 37239385, 2023). "Risk factors for PTC include iodine deficiency, prior radiation exposure to the thyroid gland and familial cancer syndromes (Cowden, DICER1, APC‐associated polyposis and Carney complex)." (PMID 36382588, 2022). "Thyroid tumours may be seen in certain syndromes, such as the Carney complex, familial adenomatous polyposis, and Cowden, DICER1, Werner, McCune Albright and Li‐Fraumeni syndromes." (PMID 36382588, 2022). "These include familial isolated pituitary tumor (FIPA; AIP), multiple endocrine neoplasia type 1 (MEN1) and type 4 (CDKN1B), Carney complex (PRKAR1A), and DICER 1 syndrome (DICER1)." (PMID 31726770, 2019).
corticotrope adenomas (3 papers, 2020 to 2025). "We describe, for the first time, rare variants in the DICER1 gene in seven patients presenting with isolated corticotropinomas and CD arising during childhood." (PMID 32714280, 2020). "In conclusion, the identification of seven pediatric patients with corticotropinomas harboring heterozygous DICER1 variants revealed a possible role for DICER1 gene defects in corticotroph tumorigenesis." (PMID 32714280, 2020). "Supporting this hypothesis, we detected seven infrequent missense germline DICER1 variants in an equal number of pediatric patients with apparently sporadic corticotropinomas." (PMID 32714280, 2020). "Therefore, although non-syndromic corticotropinomas could be a new DICER1-associated phenotype, at the moment we cannot confidently determine whether the variants found in our patients are indeed causative or if they could act as disease modifiers." (PMID 32714280, 2020).
depression (3 papers, 2015 to 2019). "Here we found that decreased DICER1 expression in blood was associated with greater amygdala reactivity to threat stimuli and to PTSD and depression symptom severity." (PMID 26632874, 2015). "In summary, this is the first human study to our knowledge to suggest that DICER1 and the miRNA regulation pathway are implicated in biological mechanisms of PTSD with comorbid depression." (PMID 26632874, 2015). "As our primary interest was to understand mechanisms underlying effects of DICER1 expression on symptoms of PTSD and depression, we investigated how DICER1 blood mRNA level might be related to neural responses to threat stimuli using fMRI." (PMID 26632874, 2015). "We examined DICER1 expression level in the Detroit Neighborhood Health Study (DNHS) cohort of 111 participants, out of whom 15 were cases of current PTSD (and 60% of these cases had comorbid current depression) and 96 were controls with no current PTSD and no current depression." (PMID 26632874, 2015).
diabetes mellitus type 2 (3 papers, 2019 to 2022). "Primary cells isolated from the adipose or skeletal muscle tissues of type 2 diabetes patients expressed lower levels of DICER1 protein and higher levels of Alu RNA compared with the cells of nondiabetic individuals." (PMID 32968070, 2020).
endometrial tumors (3 papers, 2019 to 2025). "In addition, mutations in DICER1 occur in various cancers, e.g., sporadic pleuropulmonary blastoma; gonadal, Wilms, and endometrial tumors; and anaplastic sarcomas of the kidney." (PMID 40862798, 2025). "Finally, examination of DICER1 hotspot endometrial tumors reveals derepression of specific miRNA target signatures." (PMID 31417090, 2019). "In one study of 290 endometrial tumors, six (2%) harbored DICER1 somatic hotspot variation." (PMID 30672147, 2019).
epithelial ovarian tumors (3 papers, 2019 to 2021). "Successively, the authors explored this region by Sanger sequencing, in additional ovarian tumors samples discovering DICER1 mutations in 30 of 102 non-epithelial ovarian tumors (29%)." (PMID 33922805, 2021). "Strikingly, when excluding ovarian epithelial tumor, 9/12 lowest mi53 scores involved DICER1 RNase IIIb hotspots, emphasizing how distinct their miRNA profiles are across the entire TCGA cohort." (PMID 31417090, 2019).
fibrosis (3 papers, 2019 to 2023). the formation of excess fibrous connective tissue in an organ or tissue in a reparative or reactive process. "Importantly, it was shown that suppression of Dicer1 expression in the myofibroblast-rich fibroblastic focus core mediated ECM sustained fibrosis progression in idiopathic pulmonary fibrosis." (PMID 32443855, 2020). "Some proteins of these genes have already been associated with pathophysiological processes in the kidney: in tubulointerstitial fibrosis (c-MYC, PTEN, STAT3, HIF-1α, PT53); podocyte injury (EGFR, PT53, CTNNB1, CREB1); epithelial-mesenchymal transition (PTEN); and glomerulosclerosis (DICER1, IL1β)." (PMID 37035314, 2023).
hereditary cancer syndromes (3 papers, 2023 to 2024). "As for the previous hereditary cancer syndromes related to breast cancer, there are some hereditary cancer syndromes related to ovarian cancer which are characterized by a typical phenotype: DICER1 tumor predisposition, LS, and MAP-associated polyposis." (PMID 37239385, 2023).
kidney tumors (3 papers, 2018 to 2023). "Furthermore, patients with kidney tumors within the SARC DICER1 class were significantly older than patients with kidney tumors of class LGMT DICER1 (median age: 8.8 years vs. 1.2 years, respectively)." (PMID 36966138, 2023).
laryngeal carcinoma (3 papers, 2015 to 2024). Carcinoma that arises from the laryngeal epithelium. "We have found an association between risk of laryngeal cancer and two DICER1 SNPs: rs13078 and rs3742330." (PMID 26688807, 2015). "A previous report demonstrated the direct binding of miR-892a to the 3′UTR of DICER1 transcripts in a human laryngeal-cancer-derived cell line with a consequent reduction in DICER1 protein levels." (PMID 39202414, 2024). "Our results suggest that rs3742330 of DICER1, rs13078 of DICER1, and rs784567 of TARBP2 as well as rs11077 of XPO5 might be associated with a risk of laryngeal cancer occurrence in the Polish population." (PMID 26688807, 2015).
lymphopenia (3 papers, 2019 to 2023). Reduction in the number of lymphocytes. "In the present study, we demonstrate that T cell-specific deficiency in let-7 miRNAs results in peripheral T cell lymphopenia resembling that of Dicer1 knockout mice." (PMID 31130952, 2019).
metastatic disease (3 papers, 2014 to 2025). "In contrast, DICER1 mutations were significantly more prevalent in primary tumors, with 10 mutations (16.13%) compared to 1 mutation (1.96%) in metastatic tumors (p < 0.02)." (PMID 41590496, 2025). "NRAS mutations were significantly more frequent in metastatic tumors (42.2%) compared to primary tumors (29.2%), while DICER1 mutations were more common in primary tumors (16.13% vs. 1.96% in metastases, p < 0.02)." (PMID 41590496, 2025).